MC4R (melanocortin 4 receptor)
Diseases named in the same sentence as MC4R in open-access papers (continued):
Sharing a sentence is not in itself a finding about the gene and the disease.
Obesity (continued). "A statistically significant difference was found in physical activity of different genotypes of MC4R rs17782313 in individuals with obesity (p < 0.001) and all subjects (p < 0.001)." (PMID 36123585, 2022). "The α-MSH analog setmelanotide is approved for some homozygous monogenic mutations (LEPR, MC4R, POMC, PCSK1) in the leptin–melanocortin pathway to treat severe obesity and is being studied for heterozygous mutations as well." (PMID 35447963, 2022). "Other genes that can predispose individuals to obesity include the fat mass and obesity-associated (FTO) gene, leptin receptor (LEPR), and melanocortin-4 receptor (MCR4)." (PMID 36012526, 2022). "The present work, therefore, focuses on the evaluation of the association of clinical markers related to obesity and SNPs of the LEP, LEPR, POMC, PCSK1, and MC4R genes in a healthy Mexican population." (PMID 35741707, 2022). "Nevertheless, in patients with some mutations, for example, in the melanocortin-4 receptor gene (MC4R), the BMI trajectories are similar to those of patients with simple obesity." (PMID 36479220, 2022). "In the present study, we investigated the interaction between HBI and BMI-GRS, including MC4R (rs17782313), CAV-1 (rs38 07992), and Cry1 (rs2287161) on abdominal obesity and markers for metabolically associated obesity status in overweight and obese women." (PMID 36167582, 2022). "The same MC4R variant (rs17782313) and an FTO variant (rs9930506) were significantly associated with obesity in children, reported in multiple separate studies involving thousands of individual subjects, particularly Caucasians and Asians." (PMID 36232301, 2022). "In conclusion, daisaikoto showed anti-obesity effects by salvaging the dysfunction of brown adipose tissue in MC4R-KO mice." (PMID 35710868, 2022). "Additional studies are required by including the clinical level to clarify the biology of MC4R rs17782313 and its impact on the relationship between dietary carbohydrate intake, metabolic rate, and degree of obesity." (PMID 35538513, 2022). "Targeting macrophage activation with the DPP4 inhibitor anagliptin has also been performed in genetically obese melanocortin 4 receptor-deficient (MC4R-KO) mice, which develop hepatic steatosis, NASH, and HCC in the presence of obesity and insulin resistance." (PMID 35053615, 2022). "In past decades, a large number of GWASs have identified hundreds of genes that are associated with obesity, including FTO, MC4R and POMC, and a few of them have been established as obesity genes before." (PMID 36676030, 2022). "Deletion of this receptor in mice results in the generation of Melanocortin 4 receptor knockout (Mc4r−/−) mice, which under a normal chow diet develop late-onset obesity, hyperphagia, hyperinsulinemia, and hyperglycemia." (PMID 36555433, 2022). "Both FTO and MC4R gene variants are associated with obesity in PCOS while observational evidence indicates a direct role of the interaction between FTO and MC4R polymorphisms in the development of PCOS." (PMID 35679284, 2022). "A statistically significant difference was found in mean score of emotional eating between different genotypes of MC4R rs17782313 in individuals with obesity and all study participants (p ˂0.001)." (PMID 36123585, 2022). "This study provides insight into the potential direction toward understanding the molecular basis of MC4R dysfunction in disease progression and obesity." (PMID 35807283, 2022). "The most common gene defect is a mutation that involves the melanocortin 4 receptor gene (MC4R), which is linked to a more severe and early form of obesity." (PMID 35886152, 2022). "Melanocortin 4 receptor gene-knockout (MC4R-KO) mice are known to develop obesity with a high-fat diet." (PMID 35710868, 2022). "These mice have a mutation in the melanocortin-4 receptor gene (Mc4r), and mutations of the MC4R protein are associated with early-onset obesity in humans." (PMID 35782067, 2022).
Obesity (continued). "Setmelanotide is under consideration for other rare genetic disorders associated with obesity including Bardet–Biedl syndrome, Alstrom syndrome, POMC, and other MC4R pathway heterozygous deficiency obesities." (PMID 36232301, 2022). "Of the identified genes in our study, FTO, GNPDA2, MC4R, MTCH2, NEGR1, SH2B1, TMEM18 are unequivocally regarded as obesity genes associated with PCOS, as supported by contemporary evidence." (PMID 35679284, 2022). "Inhibition of MC4R in mice leads to obesity, secondary to a hyperphagic, hyperinsulinemia and hyperglycemic state." (PMID 35741395, 2022). "Inactivation of MC4R via knock outs results in obesity in mouse models, whereas agonists to MC4R in animal models and a small phase 1 human study induce weight loss." (PMID 35419973, 2022). "Studies have suggested a strong genetic influence affecting obesity, with the melanocortin 4 receptor (MC4R) being one of the most critical and widely investigated so far." (PMID 35807283, 2022). "Our study aimed to evaluate the associations between the MC4R rs17782313, LEP rs7799039, and LEPR rs1137101 polymorphisms with obesity-related parameters in childhood and adulthood." (PMID 34205732, 2021). "After mapping the human genome, broad association studies (GWAS) have managed to identify a variety of genes involved in the etiology of obesity, among them MC4R, FTO, and PPAR family genes." (PMID 34422027, 2021). "The modern approach for treating melanocortin obesity is designing MC4R agonists; however, MC4R agonists are only effective when upstream, but not downstream, MC4R signaling is impaired, and, in addition, they can cause side effects." (PMID 34943946, 2021). "In adulthood, odds of obesity and metabolic syndrome was higher in MC4R CT/CC genotype than TT genotype carriers (OR 1.8; 95% CI 1.2–2.8 and OR 1.6; 95% CI 1.1–2.4, respectively)." (PMID 34205732, 2021). "For common variants, PheWAS analyses independently replicated the GWAS findings with strong association of multiple MC4R variants to ICD9 codes related to overweight, obesity, and morbid obesity (best P = 6.74 × 10−13)." (PMID 32952152, 2021). "Variants in MC4R, SEC16B and TMEM18 that associated with coffee consumption in previous GWAS are also GWAS-confirmed obesity loci." (PMID 34903748, 2021). "This is the first pivotal phase 3 clinical trial to investigate the safety and efficacy of an MC4R agonist for the treatment of obesity and hyperphagia in individuals with BBS or Alström syndrome." (PMID 34013094, 2021). "The relative risk analysis for of FTO, MC4R, ACE and MTHFR gene polymorphism with obesity and dyslipidaemia is performed independently in both the studied populations." (PMID 34414818, 2021). "In conclusion, the associations of the MC4R and LEP gene polymorphisms with obesity-related parameters strengthened with age." (PMID 34205732, 2021). "For obesity treatment, another agonist of MC4r, PL-8905 (a cyclic peptide), also shows high selectivity for this receptor over MC1r, presents minimal side effects on blood pressure, and has significant chemical and metabolic stability." (PMID 34066399, 2021). "The identified associations of MC4R and LEP polymorphisms with obesity-related parameters should be considered as risk factors for age- and gender-related obesity development." (PMID 34205732, 2021). "Several polygenic variants (e.g., FTO, MC4R, TMEM18, SEIC6B) increase T2D risk mediated by their obesity-predisposing effects in populations of European ancestry." (PMID 33542413, 2021). "In this study, we evaluate and catalog the MC4R sequencing and genotyping data from eMERGE III participants to further study this genomic region and its association with obesity and related phenotypes." (PMID 32952152, 2021). "Our findings are in line with the previous studies showing that physical activity can attenuate the effect of the MC4R rs17782313 on obesity." (PMID 34205732, 2021).
Obesity (continued). "The obesity-protecting MC4R mutants (V103I and I251L) showed increased presence at the PM with normal (V103I) or reduced (I251L) agonist-induced internalization." (PMID 33761344, 2021). "Recently, the MC4R agonist Setmelanotide has been approved by the Food and Drug Administration for the treatment of obesity." (PMID 34512392, 2021). "The numerous adverse effects of known MCR ligands call for the discovery of more selective ligands for specific MCR subtypes, particularly the MC4R, as the globally increasing prevalence of human obesity is a growing medical and socioeconomic problem." (PMID 34561620, 2021). "Selective restoration of MC4R expression in cholinergic neurons of obese MC4RloxTB/loxTB mice not only partially ameliorate obesity but also improve glucose homeostasis." (PMID 34262481, 2021). "Carriers of MC4R mutations display metabolic anomalies including increased energy intake, obesity and hyperinsulinemia, and the severity of these symptoms are correlated with the amount of functional MC4R." (PMID 33716966, 2021). "Another example are several MC4R mutants which lead to monogenic obesity; some the mutant MC4Rs are misfolded proteins retained intracellularly." (PMID 34830210, 2021). "The role of MRAP2 in melanin signaling is unclear, but loss-of-function MRAP2 variants are associated with obesity, which also involves α-MSH, Mc1R, and MC4R signaling." (PMID 34436011, 2021). "We used this model, mimicking features of human conformational MC4R obesity, to assess in vivo the potential efficacy of our MC4R-selective PC candidate, PC UM0130866." (PMID 33434184, 2021). "As a result, common variants in the melanocortin 4 receptor (MC4R) gene or fat mass- and obesity-associated (FTO) genes have been listed as obesity-associated SNPs in the GWAS catalog." (PMID 34162918, 2021). "Another missense variant I251L originally classified as functionally neutral shows increased MC4R basal activity through alteration of cAMP signal transduction that protects against obesity (OR = 0.5)." (PMID 32952152, 2021). "The increased affinity of plasmatic IgG for acyl-ghrelin in obesity was associated with increased ghrelin function, while increased plasma IgG/α-MSH affinity in obesity was shown to decrease activation of MC4R." (PMID 33953692, 2021). "As such, the increased presence of obesity-protecting MC4R mutants at the PM is likely to be explained by accelerated recycling to the PM for V103I MC4R and reduced internalization for I251L MC4R." (PMID 33761344, 2021). "Since diabetes is often associated with obesity, the genes related to obesity, such as FTO and MC4R, are often connected with diabetes." (PMID 34943006, 2021). "Our findings suggest that associations of the common MC4R SNPs with obesity and its metabolic complications may be dependent on the daily dietary intake, which may open new areas for developing personalised diets for preventing and treating obesity and obesity-related comorbidities." (PMID 34769477, 2021). "Although Ay females exhibited a greater degree of obesity than males in the present experiment, their metabolic disorders were less pronounced, as was also seen in MC4R knockout mice." (PMID 34943946, 2021). "We constructed a genetic risk score (GRS) based on five genetic variants (MC4R rs17782313, BDNF rs6265, FTO rs1421085, TMEM18 rs7561317, and NEGR1 rs2815752) and examined its association with obesity-related traits in a sample of Pakistanis." (PMID 33859285, 2021). "Despite interactions between MC4R genes and dietary factors on obesity and other metabolic traits have been investigated in several studies, significant results have been reported only in limited number of investigations." (PMID 32019489, 2020). "Melanocortin 4 receptor (MC4R) deficiency, caused by mutations in MC4R, is the most common cause of monogenic forms of obesity." (PMID 32692746, 2020).
Obesity (continued). "Cumulative caloric intake of vehicle-treated MC4R KO mice was 1.5 times higher compared to control mice, indicating that WD-fed MC4R KO mice had an obesity phenotype due in part to overeating as previously reported." (PMID 31990961, 2020). "Among them, the SNP rs17782313, mapping to a locus 188kb downstream from the coding sequence of MC4R gene region, has become increasingly relevant in relation to obesity and aberrant eating behaviors." (PMID 33202557, 2020). "Several obesity susceptibility loci in genes, including GNPDA2, SH2B1, TMEM18, MTCH2, CDKAL1, FAIM2, and MC4R, have been identified by genome-wide association studies." (PMID 32228543, 2020). "Genome-wide association studies have identified single nucleotide polymorphisms (SNPs) near the melanocortin 4 receptor (MC4R), gene which are associated with risk of obesity." (PMID 32899047, 2020). "In some of our previous studies, we also reported gender-specific association of the other variants such as MC4R rs17782313, FTO rs9939609, and LEP rs7799039 with overweight/obesity and related anthropometric traits in Pakistani females." (PMID 32419576, 2020). "An example of this is the interaction of two well-known obesity variants (FTO rs9939609 and MC4R rs17782313) with lifestyle measured." (PMID 32982666, 2020). "Targeted deletion of Mc4r increases food intake and decreases energy expenditure, resulting in obesity in mice." (PMID 32922362, 2020). "Mutations in these genes, such as melanocortin 4 receptor (MC4R), have been associated with monogenic obesity." (PMID 32982666, 2020). "Its anorexigenic mechanism of action relies on its ability to cross the blood-brain barrier (BBB) and activate the melanocortin four receptor (MC4R)-dependent pathway, one of the most potent currently known regulators of obesity." (PMID 33231171, 2020). "The study demonstrated that changes in lifestyle by implementing physical activity and adherence to a Mediterranean diet can modulate the obesity risk conferred by FTO and MC4R variants." (PMID 32982666, 2020). "For example, the MC4-R activation plays an important role in weight regulation, which provides insight into the mechanisms that can be used as a new target for obesity." (PMID 32722640, 2020). "Melanocortin receptor 4 (MC4R), fat mass and obesity-associated (FTO), LEP, TBC1D1 and GHR genes are correlated with growth and carcass traits in rabbit." (PMID 32575740, 2020). "Obesity caused by other genetic mutations in the leptin-melanocortin pathway include proopiomelanocortin (POMC) and melanocortin receptor 4 (MC4R), brain-derived neurotrophic factor (BDNF), and the tyrosine kinase receptor B (NTRK2) genes." (PMID 33511092, 2020). "Second, the datasets used in this work should not be regarded as complete atlases because they are likely to miss relevant cell types such as Mc4r-positive neurons, which are known to play a key role in obesity." (PMID 32955435, 2020). "Many of the pathogenic mutations that cause severe early onset obesity affect genes and proteins in the leptin-melanocortin pathways (e.g., LEP, LEPR, POMC, PCSK1, and MC4R)." (PMID 32692746, 2020). "Associations of the loci SH2B1 (rs7498665), near GNPDA2 (rs10938397), MTCH2 (rs10838738), and near MC4R (rs12970134) with obesity have been shown in many studies." (PMID 32228543, 2020). "Loss-of-function mutations in human β-MSH are associated with obesity, despite the presence of functional α-MSH, suggesting that the overall dose of α- and β-MSH is critical for MC4R activation in the paraventricular nucleus." (PMID 32369484, 2020). "Our research utilizes the multi-dimensional dimensionality reduction (MDR) method to analyze the correlation between the MC4R SNPs based on haplotype clustering and gene × environment (G × E) interactions on obesity in the Maonan population." (PMID 32770936, 2020). "In summary, our study investigated the potential interactions between the MC4R SNPs, environment and obesity in the Maonan population." (PMID 32770936, 2020).
Obesity (continued). "The genotypic and allelic frequencies of three MC4R SNPs were significantly different between the obesity and control participants." (PMID 32770936, 2020). "It has been suggested that defects in constitutive activity of MC4R in the cAMP pathway attenuate the tonic satiety signal resulting in dysfunctional energy balance and obesity." (PMID 33076233, 2020). "Specifically, genetic disruption of POMC/Pomc and MC4R/Mc4r promotes severe hyperphagia and obesity." (PMID 32166324, 2020). "This is of importance, as there is now growing evidence that more MC4R pathways are relevant for the development of obesity than previously expected." (PMID 32059383, 2020). "MC4R impairment is the most common form of monogenic obesity (6% of obesity cases) and was reported to have a codominant mode of inheritance." (PMID 33362866, 2020). "Further, MC4R is constitutively expressed in the hypothalamus and is involved in the regulation of feeding behavior, energy homeostasis, and obesity development." (PMID 33415144, 2020). "Seven SNPs were also associated with obesity in Central Mexican children (SEC16B rs543874, OLFM4 rs12429545, rs9568856, FTO rs9939609, MC4R rs6567160, GNPDA23 rs1330484, and LMX1B rs3829849)." (PMID 31936053, 2020). "Deficiency in POMC with consequent inactivation of MC4R by α-MSH reduction causes hyperphagia, severe obesity, and red hair." (PMID 33261141, 2020). "Many genes associated with obesity are also increasingly known, such as the obesity (OB) gene, fat mass and obesity-related (FTO) gene, melanocortin receptor (MC4R) gene, etc.." (PMID 32111069, 2020). "In this context, this study aimed to sequence the MC4R gene in a Brazilian cohort of adults with severe obesity." (PMID 33362866, 2020). "To date, several of the most studied SNPs, including FTO (fat mass and obesity-related) gene, MC4R (melanocortin receptor) gene, and others, have made researchers increasingly aware of the impact of SNP on the development of obesity." (PMID 32357537, 2020). "Genetically obese melanocortin 4 receptor–deficient (MC4R-KO) mice fed Western diet are a murine model that sequentially develops hepatic steatosis, NASH, and HCC in the presence of obesity and insulin resistance." (PMID 31969650, 2020). "The exogenous infusion of BDNF reversed MC4R induced obesity and hyperphagia partially in agouti lethal yellow mice." (PMID 32272767, 2020). "The most contributing SNP to this consortium was rs1801253-ADRB1, as well as other obesity risk-associated SNPs (UCP2, ADIPOQ, LEP, MC4R, etc.)." (PMID 32398726, 2020). "In this study, we put forward MC4R rs12970134 conferred an increased GDM risk, further confirming the genetic similarity between GDM and obesity or metabolic diseases." (PMID 32390949, 2020). "Fani L., Bak S., Delhanty P., van Rossum E.F.C., van den Akker E.L.T.The melanocortin-4 receptor as target for obesity treatment: a systematicreview of emerging pharmacological therapeutic options.Int." (PMID 33659800, 2020). "The minor allelic frequency of the MC4R rs17782313C, rs476828C and rs12970134A was higher in obesity than in control groups (13.8% vs. 8.3%, P < 0.001, 17.1% vs. 10.9%, P < 0.001; and 15.5% vs. 11.5%, P < 0.001; respectively)." (PMID 32770936, 2020). "Pathogenic variants in genes involved in the hypothalamic leptin–melanocortin pathway, including melanocortin-4-receptor (MC4R), have been associated with monogenic obesity." (PMID 32153512, 2020). "It seems that genes related to obesity pathology (FTO, ADIPOQ, and MC4R), in genomic research association, are related to metabolic aspects and BMI in PCOS patients." (PMID 32133054, 2019). "Although many genetic variants have been repeatedly associated with obesity, such as those located within FTO or MC4R genes, their ability to stratify obesity remains insufficient, as compared to traditional risk factors or familial resemblance." (PMID 31649740, 2019).